BRAF (B-Raf proto-oncogene, serine/threonine kinase)
Diseases named in the same sentence as BRAF in open-access papers (continued):
Sharing a sentence is not in itself a finding about the gene and the disease.
melanoma (continued). "We employed a hypothesis-driven approach to interrogate the gene expression and predictive potential of a panel of 18 cancer-associated proteins previously detected in a BRAF inhibitor-resistant melanoma cell line." (PMID 37176114, 2023). "The BRAF mutation is associated with reduced survival compared to wild-type melanoma." (PMID 37760556, 2023). "Similarly, the identification of BRAF mutations in melanoma led to the development of targeted therapies such as vemurafenib and dabrafenib, which have also improved patient outcomes." (PMID 37550388, 2023). "Retrospective analysis was carried out in 70 serum samples derived from BRAF-mutated melanoma patients treated with MAPKi in order to discover a possible “mini-signature” identifying ones who could benefit from therapy." (PMID 36835424, 2023). "BRAF inhibitors have demonstrated a substantial degree of efficacy in the treatment of patients with melanoma carrying BRAF V600 mutations; however, as is the case with other chemotherapeutic agents, resistance development constrains the clinical utility of these drugs." (PMID 37834222, 2023). "Moreover, the discovery of BRAF mutations in several cancers including melanoma led to the development of BRAF kinase and MEK kinase inhibitors." (PMID 36835424, 2023). "Regarding BRAF-MEK inhibitors, protein kinase inhibitors used in BRAF-mutated melanoma, such as dabrafenib and trametinib, their impact on the fertility of women is unknown." (PMID 37240854, 2023). "Activating BRAF mutations occurs in 50–60% of malignant melanomas." (PMID 36768289, 2023). "BRAF V600 is the most encountered mutation in melanoma, followed by NRAS mutations." (PMID 37373134, 2023). "These melanoma cell lines contain different mutations in genes such as BRAF and NRAS which activate the same cell signalling pathways as that of the integrin ligation, so this could affect their responsiveness to integrin antagonists." (PMID 37627051, 2023). "In melanoma, it has been explored in 2018 by Costa Svedman demonstrating that some miRNAs transported by circulating EVs increased during treatment with MAPKis in BRAF mutated MM patients." (PMID 37759291, 2023). "Melanoma formation is driven by mutations in the BRAF and NRAS oncogenes." (PMID 37993971, 2023). "Patients with BRAF V600E variant melanoma brain metastases may thus benefit from alternative CNS-penetrant systemic regimens." (PMID 37589977, 2023). "Available evidence shows that BRAFi/MEKi may provide rapid disease control in a relatively high proportion of patients with BRAF-mutated melanoma, although the development of secondary resistance limits the DORs." (PMID 36995534, 2023). "Approved for treating advanced melanoma patients with BRAF V600 mutations, drugs like vemurafenib, dabrafenib, and encorafenib serve as oral small-molecule inhibitors that specifically target BRAF kinase." (PMID 38021761, 2023). "Some RTK family members like EGFR may be expressed in MITF-low melanoma cells, and under this circumstance, the EGFR expression is linked to a pro-invasive and pro-metastatic melanoma phenotype with resistance to BRAF/MEK inhibitors." (PMID 36747120, 2023). "Similarly, BRAF amplifications or BRAF splicing variants promote resistance to BRAF‐targeted therapy in melanoma." (PMID 37638338, 2023). "Additionally, while patients with melanomas harboring a different mutation, BRAF V600K, respond to BRAFi, they have been shown to have shorter PFS compared to BRAF V600E mutant melanomas with this therapy but exhibit superior clinical response to ICI." (PMID 37900283, 2023). "Mutant BRAF has been implicated in the pathogenesis of different types of cancer, including thyroid carcinoma, colorectal carcinoma, non-small cell lung carcinoma, ovarian carcinoma, gliomas, melanoma, and gastrointestinal stromal tumor (GIST)." (PMID 36835466, 2023). "Furthermore, BMs are more likely to present asymptomatically at diagnosis in oncogene-addicted NSCLC and BRAF-mutated melanoma." (PMID 37484759, 2023).
melanoma (continued). "Overall, the findings demonstrated that vemurafenib might be effective in non-melanoma cancers carrying the BRAF V600E mutation, including NSCLC." (PMID 37111737, 2023). "The results obtained by liquid chromatography-tandem mass spectrometry (LC-MS/MS) demonstrate that significant differences exist in the protein landscape expressed under identical cell culture conditions by A2058 and A375 human melanoma cells, both harboring the same BRAF(V600E)-activating mutation." (PMID 37445731, 2023). "Recently in ASCO Annual meeting, a multicenter real‐world data of adjuvant treatment from German with 288 Stage III BRAF‐mutant melanoma patients identified, also showed that risk of recurrence was higher and earlier for immunotherapy than for targeted therapy." (PMID 37016119, 2023). "Furthermore, mutational activation of BRAF in melanoma promotes β‐TrCP expression and induces NF‐κB activation and melanoma cell growth." (PMID 36881608, 2023). "However, our previous work showed a significant induction of oxidatively-induced DNA strand break repair downstream of variant MC1R in BRAF-mutated human melanoma cells." (PMID 37762683, 2023). "Well-known BRAF mutations have been reported in up to 20% of all types of cancers, and BRAF V600E targeting agents such as dabrafenib, vemurafenib, and encorafenib are used to treat melanoma, lung cancer, and colorectal cancer." (PMID 38137485, 2023). "Finally, we demonstrated that the inhibition of TERT reduced the growth of BRAF-mutated melanoma including resistant cells." (PMID 37296851, 2023). "In addition, a high hsa-miR-125b expression was associated with the BRAF V600E status, which was disclosed in the results of the experiment on melanoma in cell culture." (PMID 36980957, 2023). "Most melanomas with BRAFV600 mutations regress in response to BRAF/MEK inhibitors (BRAFi/MEKi)." (PMID 37838724, 2023). "BRAF inhibitors are commonly used in melanomas where the BRAF kinase may become mutated to become overactive." (PMID 37485446, 2023). "BRAF is one of the major mutated genes in melanoma, according to the Cancer Genome Atlas (TCGA)." (PMID 37205993, 2023). "BRAF mutations are the most predominant in melanoma development." (PMID 37745303, 2023). "It has been demonstrated that BRAF mutations resulted in increased mRNA Nrf2 levels; however, accumulating evidence showed that post-translational mechanisms regulating Nrf2 protein content mainly occur in melanoma." (PMID 37372043, 2023). "However, the indication for vemurafenib in Japan is limited to unresectable malignant melanoma with BRAF mutation." (PMID 37908458, 2023). "These strong effects recommend S63845 for combination treatment with MAPK inhibitors, which may apply to approved BRAF inhibitors in BRAF-mutated melanomas, as well as to combinations of SCH772984/S63845 in both BRAF-mutated and BRAF-WT melanomas." (PMID 36902392, 2023). "These distinct melanoma subtypes prevalent in Asians may harbor unique genetic differences, such as a predilection for BRAF or N-RAS mutations or other chromosomal abnormalities." (PMID 38264654, 2023). "The observation that HMT compromises BRAF stability could also be of interest to explain the effect of these hypomethylating therapies on BRAF-mutated melanomas." (PMID 37996408, 2023). "For example, it is well established that activation of the mitogen‐activated protein kinase (MAPK) pathway is critical for melanoma development, with the mutation of genes such as BRAF, NRAS and NF1 defining around three‐quarters of non‐acral cutaneous melanoma cases." (PMID 36219477, 2023). "Taking advantage of these biological characteristics and the genetic background, mostly represented by BRAF mutations in about 50% of melanoma patients, immunotherapy and targeted therapy have been developed as standard therapies for melanoma patients with advanced disease." (PMID 36768978, 2023).
melanoma (continued). "Similarly, one BRAF(V600E) splicing variant lacks the binding domain of the RAF inhibitor vemurafenib, leading to acquired drug resistance in melanoma patients with BRAF mutations." (PMID 37635865, 2023). "In addition, the combination of vemurafenib and tubulin inhibitor ABI-274 has been proved to overcome the resistance caused by vemurafenib in BRAF-mutant melanomas." (PMID 36834830, 2023). "Moreover, melanoma with low MITF expression is associated with resistance to BRAF inhibition therapy due to reactivation of ERK in the MAPK pathway." (PMID 37239381, 2023). "Genetic alterations, primarily affecting the mitogen-activated protein kinase (MAPK) signaling pathway, have been identified in melanoma, majority of which is clustered on gain-of-function mutations in BRAF, a cell-signaling molecule that regulates the MAPK pathway." (PMID 36670319, 2023). "BRAF mutations are frequently found in melanoma and targeted therapies against these specific genetic modifications have significantly changed the management of melanoma patients." (PMID 37627054, 2023). "The main question of this study was whether there is a correlation between the histological characteristics of melanomas and the quantity (DNA yield) and quality (BRAF mutation status) of cfDNA from peripheral blood." (PMID 37958315, 2023). "In contrast, immunotherapy may potentially enhance the response to targeted therapy in BRAF-mutated melanoma, thereby prolonging tumor regression durability." (PMID 37568570, 2023). "Interestingly, BRAF had a high mutation frequency in C2, and BRAF mutations have been shown to be a driver of poor prognosis in melanoma patients." (PMID 37924160, 2023). "In conclusion, combined inhibition of ERK and Mcl-1 revealed an impressive efficacy both in BRAF-mutated and WT melanoma cells, and may thus represent a new strategy for overcoming drug resistance." (PMID 36902392, 2023). "Although RAC1 inhibitor drugs are not currently available in clinical practice, SRF/MRTF inhibitors in combination with BRAF inhibitors have recently been shown to be effective in the treatment of BRAF mutant melanoma cells with a co-occurring RAC1 P29S mutation." (PMID 36901733, 2023). "Interestingly, HO-1 was found to be upregulated in a series of BRAF-mutated melanoma cells exposed for 24 h to vemurafenib." (PMID 37372043, 2023). "As a significant proportion of melanoma is BRAF-mutated, targeted therapy may be beneficial in the neoadjuvant setting, and in combination with immunotherapy." (PMID 37444454, 2023). "Hence, future experiments on a combined treatment using BRAFi/MEKi with GP-2250 in BRAF-mutated melanoma cell lines are warranted." (PMID 37895015, 2023). "Oncogenic BRAF controls many aspects of melanoma cell biology and the common presence of BRAF mutations in nevi, primary, and metastatic melanoma suggests that this phenomenon is an early event in melanomagenesis, although the role of BRAF as a prognostic marker is under debate." (PMID 37627054, 2023). "The drug has been shown to have a high affinity for BRAF, a kinase commonly mutated in metastatic melanoma, suggesting it may also show efficacy in treating melanoma." (PMID 36894939, 2023). "Restricting the use of BRAF inhibitors however, they may only be used for BRAF-mutated melanoma (about 50%), and the response to therapy is usually limited, due to the development of resistance over the course of treatment." (PMID 36902392, 2023). "Our present study sought to determine whether PI3K was a crucial downstream partner for Cdc42 in a melanoma cells line with a BRAF mutation, which is the most common mutation in cutaneous melanoma." (PMID 37114375, 2023). "BRAF is often mutated in melanoma, papillary thyroid, colorectal, and ovarian cancers." (PMID 37446128, 2023). "Notably, a genome-wide sequencing program of thousands of melanomas worldwide revealed that mutations in BRAF are most common, with reported frequencies of over 60% (Akbani 2015; Tímár and Ladányi, 2022)." (PMID 37900283, 2023).
melanoma (continued). "Further genetic tests confirmed the diagnosis of melanoma by revealing a BRAF V600E mutation." (PMID 37373134, 2023). "BRAF mutations have been described in about 50% of malignant melanoma (MM), 50% of papillary thyroid carcinoma, 5–10% of colorectal cancer (CRC), and, in a lesser extent, in lung adenocarcinomas about 2–4% of cases and low-grade glioma especially the pilocytic astrocytoma subtype." (PMID 36758042, 2023). "Subsequently, we analyzed the OS and DFS of CYTL1 in cutaneous melanoma and BRAF-mutated melanoma." (PMID 37745303, 2023). "BRAF inhibitors have shown promising results in the treatment of BRAF-mutated melanoma." (PMID 37240450, 2023). "BRAF mutations occur in half of melanomas, accounting for 75.4% and 17.2% of V600E and V600K, respectively PI3K-AKT signaling may also be a prerequisite for MBM, which can be stimulated by various astrocyte secretions." (PMID 38104104, 2023). "Thus, preliminary results suggest that a planned switch to atezolizumab after 3 months of treatment with cobimetinib + vemurafenib did not prolong PFS and OS but is feasible and safe in patients with BRAF V600-mutated melanoma." (PMID 36995534, 2023). "In relation to the optimal sequencing of treatment in this setting, the phase 3 DREAMseq trial showed that the combination of nivolumab/ipilimumab followed by BRAF/MEK inhibitor therapy, if necessary, should be the preferred sequence for patients with BRAF-mutated advanced melanoma." (PMID 37219686, 2023). "MUC1 could interact with ErbB2 and other RTKs involved in the PI3K/AKT signaling pathway, which in turn is associated with melanoma progression and acquired BRAF inhibitor resistance." (PMID 38067178, 2023). "More recently, encorafenib was approved in 2019 in combination with binimetinib for patients with unresectable or metastatic BRAF V600 mutation–positive melanoma and in combination with cetuximab for patients with metastatic colorectal cancer with BRAF V600E mutations." (PMID 37124503, 2023). "As we had demonstrated that TERT was involved in the reactivation of the MAPK pathway in BRAF-mutated melanoma cell line, we hypothesized that the combination of 6-thio-dG with BRAF inhibitor could have some additional inhibitory effects." (PMID 37296851, 2023). "Thus, in this work, G18.EE-n-BuOH was fractioned into 17 subfractions whose effect was evaluated in A375 BRAF-mutated melanoma cells." (PMID 37049869, 2023). "Notably, the effectiveness of MALAT1-ASO treatment in inhibiting the survival and proliferation of NRAS- and BRAF-mutated melanoma cells is surprising in light of MALAT1 being strongly downregulated in patient samples of melanoma." (PMID 37235843, 2023). "Cg-Prkdcscid Il2rgtm1Wjl/SzJ) mice were subcutaneously injected with three different BRAF wild-type melanoma models harboring oncogenic NRAS mutations and treated orally with encorafenib (6 mg/kg body weight, daily) with or without binimetinib (8 mg/kg body weight, twice daily)." (PMID 38067230, 2023). "The most common melanoma genomic subtype carries BRAF mutations (52%), primarily V600E." (PMID 37160873, 2023). "The most common mutation drivers found in melanoma are the activating mutations in the BRAF gene." (PMID 35267541, 2022). "To address these current limitations, we defined a gene signature for the BRAF V600E mutation, rationalizing that a gene signature that characterizes the BRAF‐related pathways will be more informative of the sensitivity of melanoma tumors to anticancer drugs than BRAF mutations." (PMID 35044091, 2022). "Mutations in BRAF exon 15 (V600) were detected in 41 (63.08%) of 65 primary melanoma tissues." (PMID 35326682, 2022). "In addition to checkpoint inhibitors, targeted therapy with BRAF and MEK inhibitors is standard care for BRAF-mutated melanoma, which accounts for almost half of all melanoma cases." (PMID 36230853, 2022).
melanoma (continued). "Various small-molecule inhibitors have been extensively studied in BRAF-mutated melanoma cells." (PMID 35310910, 2022). "Cutaneous melanomas often harbor BRAF mutations (≈50%) and to a lesser degree NRAS mutations (28%)." (PMID 35883768, 2022). "In addition, we determined the related proteins in the tumor proliferation signaling pathway Ras/Raf/MEK/ERK by Western blotting analysis, which is particularly activated in melanoma by BRAF mutation B-RafV600E/K." (PMID 36559282, 2022). "Dabrafenib was an inhibitor of BRAF kinase, which could be used solely to treat unresectable or metastatic melanoma with BRAF V600E mutation, and to treat BRAF V600E or V600K mutated melanoma combined with trametinib." (PMID 36545327, 2022). "In addition, we are the first to present data on the efficacy of the combined inhibition of the oncogenic driver BRAF by vemurafenib and high-dose ascorbate in BRAF-mutated melanoma cells." (PMID 35406796, 2022). "Interestingly, both ORR and DCR were associated with PD-L1+ PMN levels in BRAF wild type melanoma patients." (PMID 36016960, 2022). "Targeted therapies are preferred for BRAF-mutated melanoma patients because the response to immunotherapy may take longer." (PMID 36077308, 2022). "The use of orally bioavailable small molecules BRAF inhibitors has gained significant attention in oncology after the success of FDA-approved drugs targeting the BRAF V600E mutation in melanoma, papillary thyroid cancer, BRAF mutated non–small cell lung cancer and hairy cell leukemia." (PMID 36686797, 2022). "According to the latest ASCO guidelines, ipilimumab in association with nivolumab, followed by nivolumab monotherapy, is recommended for unresectable/metastatic cutaneous melanoma, alternatively to anti-PD1 or BRAF inhibitors and MEK inhibitors (the latter in the case of BRAF V600 mutated melanoma)." (PMID 36844955, 2022). "The most important mutated genes contributing to melanoma development comprise BRAF, NRAS, and NF1, all of which may upregulate the MAPK/ERK pathway and promote cell proliferation." (PMID 36143375, 2022). "Among solid tumors, the prevalence of activating somatic missense BRAF mutations, with the V600E mutational variant accounting for about 80% of mutations, occurs in malignant melanomas (60–70%), papillary and anaplastic thyroid carcinomas (40–50%) and ovarian cancers (30%)." (PMID 36230751, 2022). "In particular, the results of multiple trials were analyzed: regarding BRAF V660 mutated melanomas, the clinical trial number NCT02231775 of the standard of care group (surgery and subsequent adjuvant therapy) vs. neoadjuvant plus adjuvant dabrafenib and trametinib were conducted." (PMID 36844955, 2022). "However, in patients with melanomas harboring BRAF gene mutations, the risk of developing a distant metastasis over time was significantly affected by miR-125b, miR-200c and miR-205 levels independently." (PMID 35326682, 2022). "Furthermore, the reduction in oncogenic BRAF mutation by RNA resistance in cultured melanoma cells, restrains proliferation and elicits apoptosis through mouse xenograft models." (PMID 36551688, 2022). "Interestingly, mutations in BRAF V600E are also common in malignant melanoma and papillary thyroid carcinoma." (PMID 36077604, 2022). "Assessment of BRAF mutation status is mandatory in advanced, treatment-naïve melanoma patients." (PMID 35159044, 2022). "BRAF mutations, identified in several solid tumors and blood cancers, prompt the constitutive activation of the pathway, which has been widely documented in melanomas." (PMID 35198098, 2022).